HIF1A (hypoxia inducible factor 1 subunit alpha)
Diseases named in the same sentence as HIF1A in open-access papers (continued):
Sharing a sentence is not in itself a finding about the gene and the disease.
tumor (continued). "In the development of solid tumor, angiogenesis is insufficient to meet the rapid growth of the tumor blood supply, thus leads to local hypoxia, and up-regulates the expression of HIF-1α." (PMID 23984913, 2013). "For instance, estrogens regulate HIF-1α expression and function in a stressful environment, indicating an intricate cooperation between these two main factors mainly involved in tumor progression." (PMID 23947803, 2013). "Recent research indicates that hypericin, a structurally related anthraquinone, can decrease excessive angiogenesis by degrading HIF1α in tumor cells via a unique hypoxia- and proteasome-independent mechanism." (PMID 23671581, 2013). "Stabilization and activation of the HIF-1α transcription complex also correlates with tumor metastasis and poor prognosis in patients with cancer." (PMID 24179495, 2013). "Mechanistically, we confirmed the synergistic effects of HIF-1α and VEGF inhibition on tumor growth and on tumor endothelium by specifically knocking down HIF-1α using shRNA." (PMID 22684860, 2013). "In human tumor cell lines grown under normoxic conditions, IL-1β up-regulates the functional HIF-1α protein through a classical inflammatory signaling pathway, involving NF-κB and COX-2, resulting in VEGF secretion by the cancer cells." (PMID 23383347, 2013). "To investigate the role of HIF-1alpha in tumor development and metastasis, we established transgenic mice constitutively expressing HIF1A gene under regulation of the cytomegalovirus gene promoter." (PMID 23593116, 2013). "Giving the fact that sirtuins regulates both HIF1α and NFkB and the central role that these two transcription factors have during tumor progression, the possibility to act on sirtuins in order to control HIF1α and NFkB has drawn much attention." (PMID 23408731, 2013). "Several previous studies have provided evidence that HIF-1α plays different roles in different types of tumours." (PMID 23599780, 2013). "It was suggested that rapid tumour growth resulted in a large tumour size and areas of hypoxia, which induces the accumulation of HIF-1α." (PMID 23599780, 2013). "c-Met, known as hepatocyte growth factor receptor, is activated by HIF-1α and it is known for tumor invasion and metastasis." (PMID 23927384, 2013). "It has been demonstrated that dichloroacetate (DCA), which inhibits pyruvate dehydrogenase kinase (PDK), activates GO in mitochondria thus leading to decreased tumour growth in many cancer cell lines; this event is accompanied by the inhibition of HIF-1α." (PMID 23762063, 2013). "Growth rate, apoptosis, cell cycle parameters, and expression of mRNA for proteins associated with invasiveness and tumor microenvironment (CA IX, VEGF-A, HIF-1A, MMP-9, and TIMP-2) were analyzed." (PMID 23914349, 2013). "The indication that such a HIF-1α-mediated Warburg profile is essential to tumor progression was provided by the rescue of anchorage-independent cell growth upon forced stabilization of the transcription factor by DMOG." (PMID 24280190, 2013). "The widely shown mechanism through which they facilitate tumor growth/adaptation is the stabilization of HIF-1α, the master mediator of progression towards malignancy, via the imbalance of TCA cycle metabolites α-KG and SA." (PMID 24280190, 2013). "Various factors are thought to affect the impact of HIF-1α activation in tumor behaviour including methodology, cut off(s) and treatment modalities." (PMID 24165149, 2013). "HIF-1α, is a crucial molecule in inducing angiogenesis in growing tumor under hypoxic stress and several reports have been published on relation between HIF-1α expression and angiogenesis in head and neck and oesophageal squamous cell carcinoma." (PMID 24165149, 2013). "Tumor adaptation to hypoxia is predominantly regulated by two structurally related hypoxia inducible factors (HIFs), HIF-1α and HIF-2α." (PMID 24288553, 2013).
tumor (continued). "This review highlights the central role of HIF1α activated in hypoxic regions of the tumor, of NFkB activation and proinflammatory gene expression in transformed cells to understand their progression toward malignancy." (PMID 23408731, 2013). "Tumor cells respond to a hypoxic state by stabilizing the Hif-1α subunit of the Hypoxia-Inducible Factor (HIF) transcription factor to promote expression of various tumor- and metastasis-promoting hypoxic response genes." (PMID 23840457, 2013). "Increased HIF-1α activates target genes involved in tumor cell growth, angiogenesis, metabolism, apoptosis and metastasis." (PMID 23927384, 2013). "High CD34 Chalkley count was found to correlate with larger tumor diameter (P = 0.002), deep invasion (P < 0.001) and HIF-1α (P = 0.04), whereas high VEGF expression correlate significantly with poor tumor differentiation (P = 0.007)." (PMID 24165149, 2013). "HIF-1α activation correlates with metastasis in many kinds of tumors and promotes metastasis through the regulation of key factors governing tumor cell metastatic potential." (PMID 23496980, 2013). "In relation to the inhibition of HIF-1α, although there is no direct relationship established between HIF-1α and CBF, several previous studies showed that digoxin and other cardiac glycosides inhibit HIF-1α synthesis to retard tumour growth." (PMID 23818933, 2013). "Tumor weight in the HIF-1α-miRNA group was 1.14±0.08 g, significantly lower than that in the untreated (1.71±0.18 g) and the Scrambled group (1.75±0.26 g) (P<0.01), but differences between the untreated and Scrambled groups were not significant (P>0.05)." (PMID 23732337, 2013). "All seven studies provided information about tumor grade, but only one study showed statistically significance between HIF-1α overexpression and poor tumor grade." (PMID 23799043, 2013). "A growing body of evidence shows that miRNAs are involved in regulating angiogenesis via targeting HIF-1α/VEGF/VEGFR signaling pathway in tumor development in vivo." (PMID 23951172, 2013). "It has been published that curcumin plays a pivotal role in tumour suppression via the inhibition of HIF-1α-mediated angiogenesis in MCF-7 breast cancer cells and in HepG2 hepatocellular carcinoma cells." (PMID 23762063, 2013). "HIF-1α is a multifunctional transcription factor, which has been shown to regulate tumor cell invasion and migration." (PMID 24137413, 2013). "Deregulation of these tumour suppressors in cancer results in activation of the mTOR/S6K pathway and subsequent elevation of HIF-1α and VEGF, which promote tumour angiogenesis." (PMID 22570651, 2012). "High levels of HIF-1α expression are observed in many human cancers, and correlated with tumor growth." (PMID 22442669, 2012). "Endostatin, has been shown to exert anti-angiogenesis and anti-tumor effects in a HIF-1α dependent manner." (PMID 23071744, 2012). "We noted that the accumulation of HIF-1α in the nuclei of tumor cells and the expression of VEGF-A and VEGF-C were increased in mice co-injected with 4T1 cells and M2-Mφs." (PMID 22616919, 2012). "This study was prompted by genetic evidence showing the involvement of Plk3 in tumor angiogenesis and HIF-1α regulation." (PMID 23210979, 2012). "Further studies are necessary to understand the greater complexity of TNFα-dependent stimulation of HIF-1α nuclear accumulation and its role in tumorigenesis and tumor progression." (PMID 22355351, 2012).
tumor (continued). "We observed that HIF-1α expression generally increased during tumor progression in MMTV-PyMT mice as previously observed in patients, thereby confirming that the MMTV-PyMT model is appropriate for these studies." (PMID 22225988, 2012). "With our expectation, HIF-1α level in KAI1 expressing tumor was significantly low as compared with control." (PMID 22390300, 2012). "Zinc is an inhibitor of HIF-1α in human cancers that represses important genes involved in tumor progression, such as VEGF, MDR1 and Bcl2." (PMID 23284967, 2012). "Over-expression of miR-21 target gene, PTEN, inhibits tumor angiogenesis through the down-regulation of HIF-1α and VEGF in cancer cells." (PMID 22952749, 2012). "In our experiments we observed that the tumour cells themselves had acquired vascular cell-like properties in vivo as a consequence of HIF1-α-mediated up-regulation of NRP-1." (PMID 23185562, 2012). "Given the fact that hypoxia and increased ROS are common conditions in the tumor microenvironment, it is possible that D6D expression in tumors results from the following pathway: Hypoxia/ROS → HIF-1α → SREBP-1c → D6D." (PMID 23112819, 2012). "Studies performed in cell lines or in ES cell-derived tumors indicate that HIF-1α can modulate tumor cell growth by controlling both metabolic functions and expression of angiogenic growth factors such as VEGF." (PMID 23300831, 2012). "Based on these results, STC1 expression is thought to be related to the Warburg effect, in which HIF-1α plays a key role in modulating glycolytic enzymes and reprogramming of tumor metabolism." (PMID 22200953, 2012). "The mechanism through which IL1β contributes to tumor formation is at least partly through activation of HIF1α by IL1β." (PMID 23166763, 2012). "TIMP-1 stands out as a soluble factor which does not only modulate the extracellular matrix by regulation of MMP-activity but as an inducer of HIF-1α, it also decides over cell fate by guiding tumor cells toward an invasive phenotype." (PMID 22807917, 2012). "Several other agents that have been identified as HIF-1α inhibitors including YC-1, PX-12, and PX-478 have exhibited efficacy in both in vitro and in vivo tumor models, further validating HIF as a therapeutic target." (PMID 22295124, 2012). "Overexpression of stress relevant proteins such as GSH-related enzymes and HIF1α in tumours has been shown to participate in oncogenesis and in resistance to both RT and chemotherapy." (PMID 23009663, 2012). "One would predict that this is the case, because prostaglandins, which are products of COX-2 activity, can upregulate IL-8, IL-6, VEGF, and HIF1α in tumor epithelial cells." (PMID 23216814, 2012). "Efficient deletion of HIF-1α reduced primary tumor growth and suppressed lung metastases, prolonging survival." (PMID 22225988, 2012). "The present study demonstrated that K5 can inhibit LLC tumor growth and metastasis by regulating HIF-1α and its downstream genes of VEGF and CXCR4." (PMID 23300882, 2012). "The tumor size, PVI, ER status, expression of MIB1 and HIF-1α were all significant factors strongly associated with worse prognosis (p = 0.031, p = 0.000, p = 0.000, p = 0.001 and p = 0.011, respectively)." (PMID 22439624, 2012). "HIF-1α is the master transcriptional factor that is stabilized under hypoxic conditions in growing tumors and controls tumor metabolism as well as expression of pro-angiogenic factors such as VEGF." (PMID 22514647, 2012). "Nuclear stabilization of HIF-1α in the tumor cells confirmed the presence of the in situ hypoxia (Figure." (PMID 23185562, 2012). "HIF-1α staining intensity was strong in all samples of ccRCC, and the average distribution was 66% (in 13 cases even all tumor cells nuclei expressed HIF-1α) but the incidence (presence) of HIF-1α alone was 9%." (PMID 22804960, 2012).
tumor (continued). "Overexpression of p70S6 K1 in microvascular endothelial cells enhances tumor growth and angiogenesis, while HIF-1α siRNA significantly inhibits tumor growth and angiogenesis, suggesting that endothelial p70S6 K1 controls tumor angiogenesis through HIF-1α." (PMID 23320155, 2012). "The accumulation of HIF-1α in the nuclei of tumor cells was increased in mice co-injected with 4T1 cells and M2-Mφs." (PMID 22616919, 2012). "Some tumor areas exhibited an expression of HIF-1α in a typical pattern, even though the local diffusion distances were low." (PMID 22825389, 2012). "HIF-1α is generally resided in mammal and human tissue in hypoxic condition, it has been found over-expressed in about 70% tumor." (PMID 22453051, 2012). "HIF-1α signal pathways leading to the tumor angiogenesis and invasive migration have been suggested to be key steps of tumor metastatic progression." (PMID 23300882, 2012). "Multiple studies have reported significant correlations between HIF-1a accumulation and tumor progression in several types of human cancer." (PMID 23166763, 2012). "HIF-1α is generally subjected to the negative regulation of tumor suppressors such as Von Hippel-Lindau (VHL) and phosphatase and tensin homolog (PTEN)." (PMID 23391506, 2012). "Analysis of lysates from tumor cells revealed that cycloheximide treatment prevents estrogen upregulation of HIF-1α, highlighting the importance of de novo protein synthesis in estrogen induced vasculogenesis in vitro." (PMID 23088607, 2012). "Through outlining various targets regulated by hypoxia/HIF-1α to mediate tumor metastasis, the review wishes to provide a comprehensive guide according to the various categories described." (PMID 23241400, 2012). "Tumor sections were then stained for HIF-1α immunohistochemistry and the images for both signals were merged." (PMID 22211243, 2012). "CD147 is induced by HIF-1α and Sp1 to promote glycolysis and tumor progression in epithelial solid tumors." (PMID 23241400, 2012). "The oral administration of 100 mg/kg ER-400583-00 to mice bearing U251 tumor xenografts resulted in a rapid suppression of HIF-1α that persisted for 24 h." (PMID 22211243, 2012). "Studies have shown that the reoxygenation of hypoxic tumor cells can also result in free radical formation, leading to the nuclear accumulation of HIF-1α." (PMID 22363512, 2012). "This indicates that HIF-1α in the endothelium plays a significant role in determining the number of intravasating tumor cells in this model." (PMID 22264788, 2012). "Chemotaxis and migration of tumor cells, the key steps in cancer metastasis, are induced and driven by hypoxia and closely related to HIF-1α signal pathway." (PMID 23300882, 2012). "Stabilization of HIF-1α is also influenced by genetic alterations, as well as by growth factors, hormones and cytokines produced by both tumour and stromal cells." (PMID 23144690, 2012). "HIF-1α and HIF-2α have been linked to an aggressive tumor phenotype by promoting the processes essential for tumor growth as well as blocking differentiation." (PMID 22363512, 2012). "It has been reported that endostatin exerts anti-angiogenesis and anti-tumor effects in a HIF-1α dependent manner." (PMID 23071744, 2012). "Since a similar HIF-1α expression pattern was observed using two structurally distinct Hsp90 inhibitors, we conclude that HIF-1α regulation rather depends on the tumor cell type than on the chemical structure of the Hsp90 inhibitor." (PMID 22347438, 2012). "Immunohistochemistry was used to analyze SEMA4D expression and tumor angiogenesis-related proteins (HIF-1α and VEGF) in tissues from 40 patients with normal ovarian epithelia and 124 EOC patients." (PMID 23202951, 2012). "Activation of hypoxia-inducible factor-1 alpha (HIF-1α) plays a major role in the development of tumor phenotype, especially in aggressive tumors." (PMID 22992293, 2012). "Adaptation to hypoxic conditions is a critical step in tumor progression and is, in part, regulated by HIF-1α." (PMID 23300882, 2012).
tumor (continued). "VEGF-A, which is known as an important mediator of tumor angiogenesis, is one of the targets of HIF-1α." (PMID 22616919, 2012). "Hypoxia suppressed the degradation of HIF-1α protein and made it translocate into the tumor cell nuclei from cytoplasm and then form the HIF-1 with HIF-1β." (PMID 23762617, 2012). "Further analysis of the number of circulating GFP-tagged tumor cells in the bloodstream at the time of sacrifice indicated tumor cells in the circulation were reduced by ∼50% in tumor-bearing HIF-1α endothelial cell deletion mutants (right)." (PMID 22264788, 2012). "Endogenous HIF1α is found in the nuclei of normoxic cells from normal and tumor tissues and poly-ubiquitylated HIF1α is detected exclusively in the nuclei of normoxic HeLa cells." (PMID 22537386, 2012). "The transcription factor hypoxia-inducible factor-1 (HIF-1α) upregulates expression of a variety of target genes under hypoxic conditions, and plays a major role in determining tumor radiosensitivity." (PMID 22458929, 2012). "Semaphorin 4D is induced by HIF-1α to promote angiogenesis and enhance tumor invasive growth of head and neck cancers." (PMID 23241400, 2012). "HIF-1α is responsible for the activation of more than 60 downstream target genes involved in angiogenesis, tumor growth, and invasion." (PMID 22997517, 2012). "Plk3 has also recently been found to phosphorylate and stabilize PTEN phosphatase, a known regulator of HIF-1α and tumor angiogenesis." (PMID 23210979, 2012). "Consistent with the larger size of these tumours, the nuclear signal of HIF-1α was found to be much stronger in these tumour sections indicating a higher level of hypoxia." (PMID 23185562, 2012). "MSCs are mobilized into the circulation upon hypoxia, a general feature of solid tumors, and attracted into the tumor by factors induced by hypoxia-induced factor1α (HIF1α), including VEGF, and SDF-1α." (PMID 22844466, 2012). "To test this, we examined the effect of KAI1 on primary tumor formation and HIF-1α and VEGF expression in a tumor xenograft model." (PMID 22390300, 2012). "Only active and viable EPCs will migrate and accumulate at the margin of the tumor due to the specific migratory signals, such as HIF-1α induced SDF-1 expression." (PMID 22276177, 2012). "Because the WT and KO cells had previously been cultivated in monolayer in the presence of serum, the ability of HIF-1α to promote SFE was confirmed using tumor cells derived from freshly digested Hif1a DF, PyMT+ tumors originating in intact transgenic mice." (PMID 22225988, 2012). "Our finding implies the potential role of K5 as a promising HIF-1α-targeting molecule in the treatment of tumor growth and metastasis." (PMID 23300882, 2012). "Supporting this, PLK3 knock-out murine embryonic fibroblasts (MEFs) display significantly enhanced expression of HIF-1α and tumor angiogenesis in response to hypoxia." (PMID 23210979, 2012). "Regulation of HIF-1α is also required for effective regulation of tumor angiogenesis and tumor growth suppression." (PMID 22792362, 2012). "Our results showed for the first time that K5 inhibits both tumor growth and metastasis in LLC via the dual effects of anti-angiogenesis and suppression of tumor cell motility by targeting HIF-1α pathway." (PMID 23300882, 2012). "Both cyclooxygenase-2 (COX-2) and hypoxia inducible factor-1α (HIF-1α) have been reported to modulate VEGF-C expression in different tumor models." (PMID 22761819, 2012). "In contrast, H1339 tumor cells show an up-regulated HIF-1α expression upon Hsp90 inhibition, irrespectively of the inhibitor concentration and oxygenation status." (PMID 22347438, 2012). "Conceivably, the reduced vascular supply and CD31 expression we observed in irradiated xenografts here would be responsible for local tumour hypoxia and the enhanced expression of HIF1α we observed." (PMID 22607554, 2012).